HIF1A (hypoxia inducible factor 1 subunit alpha)
Diseases named in the same sentence as HIF1A in open-access papers (continued):
Sharing a sentence is not in itself a finding about the gene and the disease.
tumor (continued). "HIF-1α is involved in tumour angiogenesis in a variety of pathways and is one of the most promising targets for tumour angiogenesis." (PMID 33865381, 2021). "It has been reported that NO treatment can effectively inhibit the expression of HIF-1α in hypoxic tumor cells." (PMID 34399762, 2021). "Astragalus membranaceus and Curcuma wenyujin increased CD34 and reduced HIF-1α, promoted vascular normalization in tumor-derived endothelial cells of HCC." (PMID 33933107, 2021). "In summary, tanshinones can inhibit cell growth and tumor growth by regulating the expression of proangiogenic growth factors and hypoxia-inducible factor 1alpha (HIF-1α)." (PMID 35145409, 2021). "It is noteworthy that HIF-1α acts not only as a key response adapted to tumor hypoxia, but also a transcription factor controlling a plethora of target genes that promote physiological changes associated with chemo-/radioresistance." (PMID 33819917, 2021). "In this study, HIF1α-deficient NK cells are more responsive to IL18 and hindered growth of RMA-S and LLC tumour models, showing enhanced OXPHOS and NFκB activity which correlated with increased expression of IFN-γ and Granzymes." (PMID 34090499, 2021). "Mechanistically, KRAS drives the production of CSF2 and lactate in tumor cells by stabilizing hypoxia-inducible factor-1α (HIF-1α), a transcription factor that controls the expression of CSF2 and glycolytic genes." (PMID 33833221, 2021). "It is well known that the hypoxic state of the center of a tumor mass induces hypoxia inducible factor 1α/β (HIF-1α/β), that in turn incites the expression of CD39 and CD73, thereby ADO formation is promoted." (PMID 33806300, 2021). "PTGIS is a HIF-1α target gene that plays a primary regulatory role in hypoxic tumor progression by activating the transcription of various oncogenes." (PMID 34512722, 2021). "In HCC, the high expression level of HIF-1α strongly correlates with the adverse prognosis and progressive stages of the tumor." (PMID 34557407, 2021). "MJ-exposed tumor cells showed inhibition of HK 2, LDH A, PDK-1, and HIF-1α expression, which have a pivotal role in maintaining the predominant glycolytic phenotype of tumor cells, crucially required for augmented survival of neoplastic cells." (PMID 33718176, 2021). "A reduced ability of tumor cells to adapt to hypoxia and suppressed expression of hypoxia-inducible factor-1α (HIF-1α) was observed under NO-sulindac treatment." (PMID 34356634, 2021). "Hypoxia and HIF1α have been known for a long time as an intricate part of the tumor microenvironment." (PMID 34068008, 2021). "P-coumaric acid treatment was also found to significantly suppress tumor growth in a xenograft model by downregulating stem cell markers and β-catenin as well as HIF-1α signaling." (PMID 34149413, 2021). "Mitochondrial aconitase, the second enzyme of the TCA cycle, is involved in tumor development, which originates from the discovery that hypoxic conditions upregulate the HIF-1α target miR-21083,91." (PMID 33637686, 2021). "In ileal carcinoids, HIF-1α is constitutively active and associated with gene expression related to epithelial-to-mesenchymal transition (EMT) and tumor cell migration." (PMID 34316328, 2021). "LncRNA RP11-390F4.3 is induced by hypoxia/HIF-1α to facilitate EMT through modulation of multiple EMT-associated factors, leading to tumor metastasis." (PMID 34295922, 2021). "Our study found that the HIF-1α-LDHA pathway regulates the activation of anaerobic glycolysis in tumor cells and suppresses cells that are sensitive to radiotherapy and chemotherapy." (PMID 33664256, 2021). "Hypoxia, which is orchestrated by hypoxia-inducible factor-1α (HIF-1α), contributes to tumor metabolism, angiogenesis, and cell survival." (PMID 33850110, 2021). "Next to the release of immunosuppressive factors, a hypoxic tumor microenvironment also impairs anti-cancer immunity through HIF-1α-mediated upregulation of ADAM10." (PMID 34055644, 2021).
tumor (continued). "For instance, tumor-derived Leukemia inhibitory factor (LIF) transcription is enhanced by HIF1α signaling activation following cisplatin treatment." (PMID 34604066, 2021). "HIF-1α promotes tumor progression by regulating glycolysis, angiogenesis, and cell cycle progression of tumor cells." (PMID 34930376, 2021). "HIF-1α is activated in the hypoxic microenvironment of solid tumors, and promotes tumor cell survival by increasing glucose uptake and utilization." (PMID 34917504, 2021). "HIF1A overexpression promoted, whereas OR7E156P silencing inhibited tumor growth; the inhibitory effects of OR7E156P silencing on tumor growth were partially reversed by HIF1A overexpression." (PMID 34422645, 2021). "It was reported that the increased expression of HIF-1α is often detected in tumor cells with low levels of α-KG." (PMID 34425876, 2021). "Lactate produced by tumor cells has been shown to polarize M1 macrophages to an M2 phenotype mediated through increased expression of HIF-1α in TAMs." (PMID 33466735, 2021). "The major underling mechanism is the high-level expression of hypoxia-inducible factor-1α (HIF-1α) at the tumor site, a key component of HIF-1 protein." (PMID 33408777, 2021). "The analysis of HIF-1α expression in tumor tissues suggested that S4 significantly decreased about 2.5-fold in the level of hypoxia in ESCC tumors treated with radiotherapy." (PMID 34249682, 2021). "We found that hypoxia in the tumor microenvironment contributes to the repression of miR-4521 expression in a HIF1α-independent manner in GC cell." (PMID 33407516, 2021). "Deletion of the HIF-1α gene in endothelial cells (EC), has been reported to reduce neovascularization and tumor growth, by disrupting the VEGF-mediated autocrine loop in EC, which is an essential component of solid tumor angiogenesis." (PMID 33472628, 2021). "Our previous study suggested that lncRNA-NUTF2P3-001 is a potent tumor promoter, which is upregulated by HIF-1α under hypoxia microenvironment in PC." (PMID 34881179, 2021). "HIF-1α/SMAD3 then mediates the transcriptional regulation of CDCA2 in hypoxic tumours, leading to cancer cell proliferation." (PMID 34062959, 2021). "Promoter regions of HIF1α and glycolytic co‐activator proteins as well as glycolytic target genes of HIF1α are consistently demethylated in tumor and residual cells with isoform‐specific demethylations in both populations." (PMID 34694069, 2021). "Tumour tissues from intracranial transplantation also showed that both HIF1α and HIF2α were highly expressed, and these tissues had high expression of hypoxyprobeTM-1." (PMID 33986256, 2021). "For the degree of tumor hypoxia, the R2* values showed a positive correlation with HIF-1α (r=0.776, P=0.003)." (PMID 33996599, 2021). "Tumor cell-produced lactate can promote the macrophage M2 phenotype by stabilizing hypoxia-inducible factor 1-alpha (HIF-1α) and activating g protein-coupled receptor 132 (GPR132) to induce vascular endothelial growth factor." (PMID 34722510, 2021). "Promote tumor cell proliferation, migration, invasion and angiogenesis through the miR138/HIF1α axis." (PMID 34616746, 2021). "This can be inferred from a previous study that found that VEGF-A which had been induced by HIF-1α promoted tumor infiltration of CD8+ T cells through regulation of endothelium permeability and maintenance of the effector state of CD8+ T cells." (PMID 34575959, 2021). "In this trial, changes in tumor tissue (hypoxia staining with HIF1α and assessment of microvascular architecture) were determined along the window-of-opportunity in order to ascertain the accuracy of the PET scans." (PMID 33869665, 2021). "To further confirm the effect of hypoxia on the cytokine expression of macrophages co-cultured with tumor cells, we knocked down the hypoxia modulator, HIF1α, in A549 cells and analyzed the expression of IL1A and IL6." (PMID 34362882, 2021).
tumor (continued). "A set of tumor-promoting factors such as HIF-1α, ARNT, PFKFB4, and RBKS can be down-regulated by siRNA in inducing apoptosis and enhancing their sensitivity to chemotherapeutic agents including DOX and GEM." (PMID 34943856, 2021). "Along with the TFs NF‐κB, C/EBPβ, ETS2, and HIF1A that have been well‐documented as tumor promoters, JUN and its 17 downstream target genes were also categorized in this highly active module." (PMID 34459128, 2021). "Hypoxia increased ALKBH5 expression through HIF-1α, resulting in the sustaining of target gene expression and eventually enhancing the tumor stemness phenotype." (PMID 34218271, 2021). "Accordingly, Rab27a is critical for the genesis of CD19+ B cell-derived EVs from tumour-bearing mice and its transcription is controlled by HIF-1α." (PMID 34830449, 2021). "The transcription factor hypoxia-inducible factor 1α (HIF-1α) is overexpressed in human cancers due to intra-tumoral hypoxic conditions, leading to angiogenesis, survival, and proliferation of tumor cells." (PMID 34026649, 2021). "It has been well-known since the early 2000s, that the HIF1α stabilization and the elevated HIF1α protein levels are characteristic for ∼50% of tumor cells under normoxia." (PMID 34257622, 2021). "Although prolonged lack of oxygen inhibits normal cell metabolism, hypoxia promotes glycolytic phenotype in tumor cells via stabilizing HIF-1α." (PMID 34277453, 2021). "Tumor cells activate HIF-1α and c-Myc due to hypoxia, and these transcription factors bind to the promoter of LDHA, upregulating the expression of LDHA and converting more pyruvate to lactate." (PMID 33732237, 2021). "In terms of biomarkers, one study used 94 ccRCC tumor tissues to immunochemically determine the expression of nuclear HIF1α versus cytoplasmic HIF1α." (PMID 34384473, 2021). "Deletion of HIF1α in vitro decreased the tumorigenic potential of PyMT cells, as well as their ability to form tumor-initiating cells (TICs)." (PMID 33235291, 2021). "HIF-1α is a well-established oxygen sensor in tumor cells and also a modulator of glycolysis and PKM2 expression through direct regulation of the c-Myc/hnRNP splicing axis to favor PKM2 expression." (PMID 33503959, 2021). "With an increase in tumor size, the expression of HIF-1α increases as the level of hypoxia increases, which will further promote tumor development." (PMID 34930376, 2021). "HIF-1α stimulates the expression of Glut-1 to increase the intracellular glucose levels, which favor glycolysis and tumor development." (PMID 34771718, 2021). "The combination of HIF-1α inhibitors, Ado-inhibiting tumor immune microenvironment regulatory drugs, and other drugs with ICIs has good efficacy in both preclinical studies and phase I-II clinical studies." (PMID 34012727, 2021). "HIF-1α-mediated mechanisms favor tumor growth and malignant progression, up- and down-regulation of genes, as well as pathologic modifications of the genome, whereas HIF-2α stimulates some, but not all genes activated by HIF-1α." (PMID 33777815, 2021). "Taken together, our data indicate that TRAP1 is induced in a HIF1α-dependent way under both hypoxic and pseudo-hypoxic conditions, and its induction has important consequences on the in vivo metabolic rewiring of neoplasms." (PMID 33934112, 2021). "Although HIF-1α is most frequently examined to define hypoxic tumours, multi-marker strategies have been implemented previously and based on HIF sub-cellular pathways." (PMID 34298636, 2021). "HIF-1α leads to increased expression of angiogenic markers, which are important for successful growth, invasion, and metastasis of a tumor." (PMID 33639646, 2021). "Following that, under hypoxic conditions, HIF-1α knock-down diminishes the tumor lactate level, increases basal and maximal oxygen consumption rate (OCR), and sensitizes HNSCC xenografts to high-dose single-fraction radiotherapy." (PMID 34539584, 2021).
tumor (continued). "Many HIF-1α inhibitors are yet to be investigated; however, the vascular normalization when tumor growth is inhibited, and further experimental evidence showing that the small molecule HIF-1α inhibitors induce normalization of tumor vasculatures is required." (PMID 33230600, 2021). "VEGF, one of the major target genes of HIF-1α, codes for a protein that stimulates tumor angiogenesis and neovascularization, which strongly correlates with cancer cell proliferation, migration, and metastasis." (PMID 33806179, 2021). "Local hypoxia in the tumor induced by TACE can have further downstream effects on the expressions of HIF-1α and VEGF." (PMID 33685316, 2021). "Time-dependent ROC curves illustrate that the constructed model is superior to age, AJCC stage, tumor pathological grade, and HIF-1A mRNA expression in the prognostic prediction of HCC." (PMID 34917132, 2021). "Hypoxia promotes Pro and HPro production in tumor cell lines, which is a part of the hypoxia response through the regulation of HIF-1α." (PMID 34822392, 2021). "Well-known EMT inducers (Transforming growth factor beta - TGF-beta, PI3K-AKT, KRAS, c-Myc, and HIF1a) also affect tumor metabolism." (PMID 33673109, 2021). "In this context, HIF-1α overexpression led to EMT and chemoresistance while its inhibition restored chemosensitivity, highlighting a central role of hypoxia, even in tumours harbouring T790M mutation." (PMID 34298636, 2021). "The best-known hypoxia-inducible factor, 1α (HIF-1α), has been confirmed to play important roles in transcription initiation during the tumor progression." (PMID 34926261, 2021). "Activation of the PI3K/ Akt pathway in tumor cells also increases VEGF secretion through hypoxia-inducible factor 1α (HIF-1α) dependent and independent mechanisms." (PMID 33865381, 2021). "Under hypoxia state, VEGF enhanced expression and even the initial starting factor of angiogenesis in tumor tissue, while HIF-1α played a “bridge” role in the process from hypoxia to VEGF increased expression." (PMID 33688358, 2021). "Enhancement of perfusion through a new vessel network in a tumor microenvironment is often triggered by hypoxic conditions when the expression of VEGF-A is positively regulated by hypoxia-inducible factor α (HIF1α)." (PMID 34205977, 2021). "In this study, we discovered that HIF1α can positively regulate GPD1 at the transcriptional level to suppress tumor progression via inhibiting mitochondrial function and lipid metabolism." (PMID 34098990, 2021). "For example, in CC cells, HIF1α increases survivin expression, which favors tumor cell invasion and dissemination and metastasis." (PMID 34752201, 2021). "In NSCLC, HIF-1α showed a mixed cytoplasmic/nuclear expression pattern in tumor cells, tumor vessels and tumor-infiltrating macrophages, as well as in areas of metaplasia, while normal lung tissues displayed negative or very weak cytoplasmic staining." (PMID 33407675, 2021). "Among various intrinsic and extrinsic factors, HIF-1α is the key mediator of hypoxic signal transduction, controlling the expression of more than 100 genes and exerting a diverse and complex impact on tumor radiotherapy." (PMID 33869184, 2021). "This is evidenced by increased expression of HCC tumor-derived genes downstream of the Hif1α-ARNT complex." (PMID 33995488, 2021). "In agreement with our in vitro observations, HACE1 knockdown led to increased levels of HIF1α levels in tumor tissues." (PMID 33603169, 2021). "HIF-1α-mediated resistance has been demonstrated to be vital for tumor resistance to a number of chemotherapeutics, although a number of specific mechanisms have been described that are often tumor-type-dependent." (PMID 33513777, 2021). "HIF-1α expression in tumor tissue in the combination groups was lower than that in the control and DOX groups." (PMID 33546453, 2021). "HIF-1α expression rises alongside tumor grading, being higher in less differentiated than in well-differentiated lesions." (PMID 33777815, 2021).
tumor (continued). "In solid tumours, prolonged exposure to hypoxia induces HIF1α expression in tumour infiltrating NK cells and negatively regulates IL18-dependent NFκB activity." (PMID 34090499, 2021). "HIF-1α can also regulate the expression of many glycolysis-related genes and promote tumor angiogenesis." (PMID 34930376, 2021). "In the current study, we investigated the clinical significance of tumor expressions of HIF1A, VEGFA, CA9, and SLC2A1 assessed by IHC and markers of systemic inflammation (NLR and CRP) in pediatric patients with MPNST." (PMID 33810575, 2021). "The expression of BIRC3 was found to correlate with that of HIF-1α in a hypoxic tumor region, and it was shown that BIRC3 is a key molecule mediating the survival adaptation in hypoxia-driven mesenchymal GBM habitats." (PMID 33762019, 2021). "The data demonstrated that compared with HIF‐1α KO fibroblasts, HIF‐1α MOCK fibroblasts enhanced tumour cell proliferation and phenotype cloning." (PMID 33943003, 2021). "The present study was undertaken to study the association of HIF-1α with LOXL-2 in OSCC and their role in tumor progression." (PMID 33639646, 2021). "Studies have shown that HIF1α affects the regulation of tumor cell proliferation, angiogenesis, apoptosis and chemotherapy resistance during tumor development." (PMID 34221996, 2021). "A second mechanism by which TAMs upregulate tumor cell glycolysis is through the secretion of extracellular vesicles that carry a HIF-1α-stabilizing long non-coding RNA (lncRNA) termed HISLA." (PMID 34831183, 2021). "The antiangiogenic property of β-caryophyllene is attributable to its interaction with the transcription factor HIF-1α that regulates the biological pathways related to hypoxia, tumor metastasis, and tumor-mediated angiogenesis." (PMID 33916183, 2021). "In short, it appears that tumour angiogenesis in HNSCC simultaneously involves both the HIF-1α and Notch1 pathways." (PMID 34944837, 2021). "Based on the reduction of azo groups by azoreductase within the hypoxic tumor microenvironment, we have developed a hypoxia-activated self-immolative prodrug containing a HIF-1α inhibitor and a HDAC inhibitor for the first time." (PMID 34659720, 2021). "HCC tumor-derived ARNT (log2 fold change = −2.28) is a crucial gene involved in tumor progression that binds to Hif1α during hypoxic conditions to upregulate genes that contribute to invasion, metastasis, and neo angiogenesis." (PMID 33995488, 2021). "In the hypoxic tumor environment, Hypoxia Inducible Factor 1 Subunit Alpha (HIF-1α) activates BNIP3 and NIX, resulting in mitochondrial mass reduction due to the increased mitophagy flux, thus facilitating the cancer metabolic switch." (PMID 33918863, 2021). "By using a nude mice orthotopic tumor model, they also found that ELTD1 upregulates the protein expression of HIF–1α (hypoxia–inducible factor 1–alpha), a regulator of tumor formation (cell proliferation, colony formation, migration, and invasion)." (PMID 34068040, 2021). "MM cells predominantly adapt to hypoxia via the hypoxia-inducing TF Hif-1α, a critical regulator of genes contributing to epithelial-mesenchymal transition, motility, immune evasion, drug resistance, metabolic reprogramming, metastasis, and maybe most importantly to tumor-associated angiogenesis." (PMID 34007044, 2021). "HIF-1α is also capable of indirectly interfering with the tumor-suppressive ribonuclease III enzyme Dicer, a key player in the biogenesis of miRNAs." (PMID 34884541, 2021). "MEIS1 transcriptionally regulated the expression of hypoxic tumor markers, namely Hif-1α and Hif-2α, which had crucial roles in tumorigenesis." (PMID 33776902, 2021). "HIF-1α activation through persistent hypoxia is closely related to the invasive tumor phenotype and an unfavorable prognosis in patients with GC." (PMID 33856653, 2021). "Another tumour response to radiotherapy involves HIF-1α activation to enhance the radioresistance of endothelial cells needed to sustain tumour vasculature." (PMID 34830449, 2021).